EGF (epidermal growth factor)
Diseases named in the same sentence as EGF in open-access papers (continued):
Sharing a sentence is not in itself a finding about the gene and the disease.
cervical carcinoma (continued). "Results similar to those shown for ME-180 were also observed in other cell lines, including H1299, HepG2 and Hep3B cells and MEFs, indicating that EGF-driven regulation of MKRN1 and PTEN is not only restricted in cervical cancer cell lines." (PMID 26183061, 2015). "Our results indicate that H-rev107 was co-precipitated with H-RAS and downregulated the levels of activated RAS (RAS-GTP) and ELK1-mediated transactivation in epidermal growth factor-stimulated and H-RAS-cotransfected HtTA cervical cancer cells." (PMID 24884338, 2014). "EGF triggers a cascade of signaling events through interaction with its receptor, EGFR, and has been proven to be a potent inducer of EMT in cervical cancer." (PMID 23936413, 2013). "Our findings, therefore, identify a novel mechanism that mediates EGF/EGFR-induced EMT and a potential therapeutic target for cervical cancer." (PMID 23936413, 2013). "In this study, we found that TACC3 was up-regulated upon EGF stimulation, and depletion of TACC3 abolished EGF-mediated EMT process in cervical cancer cells." (PMID 23936413, 2013). "In this study, we reported that miR155 overexpression suppressed EGF-induced EMT, decreased migration/invasion capacities, inhibited cell proliferation and increased the chemo-sensitivity to DDP in human Caski cervical cancer cells." (PMID 23284982, 2012). "EGF (Epithelial growth factor) is one of the most important EMT regulatory factors that triggers EMT in a variety of solid tumours, including cervical cancer." (PMID 23284982, 2012). "EGCG exerts its anticancer effects by targeting multiple pathways in cervical cancer: it inhibits EMT and metastasis via ROS/Smad and EGF/EGFR signaling, regulates epigenetic regulators to reactivate tumor suppressor genes, and suppresses angiogenesis and matrix remodeling." (PMID 41608512, 2026). "Therefore, LY6K depletion suppresses the effects of EGF and TGF‐β along with the basal levels of proliferation, migration, and invasiveness in cervical cancer cells." (PMID 37076981, 2023). "IGF-1 and EGF were shown to stimulate the recruitment of KCC4 from a presumably inactive cytoplasmic pool of endoplasmic reticulum (ER) and Golgi to the front-end plasma membrane of migrating cervical cancer cells." (PMID 35008759, 2021). "TACC3 was previously suggested to piay a vital role in epidermal growth factor (EGF) mediated EMT, which represents a promising therapeutic strategy for the treatment of cervical carcinoma and is involved in the EGF/EGF receptor (EGFR) signal transduction pathway." (PMID 34134633, 2021). "As STAT3 can be activated by several soluble factors in cervical cancer cells, such as OSM, EGF and IL-10, it is possible that the IL-6 low cancers might be dependent on these additional cytokines to maintain active STAT3." (PMID 31226168, 2019). "For instance, Cetuximab, a chimeric immunoglobulin G2 monoclonal antibody that binds specifically to EGFR and competitively inhibits the binding of EGF and other ligands, has been developed to be used in patients with different cancers with high expression of EGFR including cervical cancers." (PMID 31470515, 2019). "To directly test whether EGFR modulates TF expression in cervical cancer, we treated CASKI cells with cetuximab one hour before recombinant epidermal growth factor (EGF)." (PMID 30093972, 2018). "Knockdown of FTS inhibits EGF-induced EMT and migratory ability of cervical cancer cells." (PMID 26356073, 2015). "Epidermal Growth Factor (EGF), Insulin Growth Factor 1 (IGF-1) and Vascular Endothelial Growth Factor (VEGF) are known to regulate cervical cancer cell proliferation and invasiveness which play key roles in determining the high-risk factors and lead to recurrence and mortality." (PMID 25070070, 2014). "Thus, BCL-3 is required for EGF-dependent EMT and for cell invasion of cervical cancer cells, at least by promoting KIAA1199 expression." (PMID 25366117, 2014).
cervical carcinoma (continued). "Moreover, Snail, a key player in EGF-mediated EMT, is found to be correlated with the expression of TACC3 in cervical cancer." (PMID 23936413, 2013). "Likewise, E7 involvement in PI3K/AKT1 activation and was relevant during the progression of cervical cancer, while, regarding the EGF pathway, Gefitinib incubation did not alter Pirin levels." (PMID 32679705, 2020). "MiR-125a-5p mimic or/and pcDNA-GALNT7 were transfected into the cervical cancer cells at the absence of epidermal growth factor (EGF) or not, and the pcDNA-GALNT7 was transfected into the cervical cancer cells at the absence of inhibitors of multiple kinases or not." (PMID 32308562, 2020). "Importantly, in the absence of TACC3, EGF is not able to induce EMT, suggesting that TACC3 is necessary for EGF-mediated EMT in cervical cancer." (PMID 23936413, 2013). "However, EGF-elicited signal transduction is not the only mechanism mediated by anti-EGFR MAbs, since these molecules can also induce ADCC and, in primary cervical cancer cell lines obtained from cervical biopsies, ADCC induction was dependent on EGFR expression." (PMID 22185378, 2011).
lung adenocarcinoma (77 papers, 2008 to 2026). A carcinoma that arises from the lung and is characterized by the presence of malignant glandular epithelial cells. "The young lung adenocarcinoma population (≤ 45 years old) is susceptible to EGF rs1897990 and rs1524106 variants, with smoking being another risk factor." (PMID 40696566, 2025). "This study indicates that the T allele variants of the EGF gene rs1897990 CT mutant were high‐frequency adverse mutations that increase the risk of lung adenocarcinoma in young patients." (PMID 40696566, 2025). "The core EGF gene variants in string interaction network rs1897990 and rs1524106 are significant risk factors for lung adenocarcinoma in young individuals, particularly when combined with smoking." (PMID 40696566, 2025). "The EGF gene variants rs1897990 and rs1524106 are significant risk factors for lung adenocarcinoma in young individuals (≤ 45 years), particularly when combined with smoking." (PMID 40696566, 2025). "The objective of this study is to investigate the genetic susceptibility and risk factors of EGF gene rs1897990 and rs1524106 in lung adenocarcinoma young patients aged ≤ 45 years." (PMID 40696566, 2025). "This is so for the family of epidermal growth factors (EGF) whose altered expression has been linked to several pathogeneses, such as lung adenocarcinoma and several other cancer types, chronic pain, chronic kidney disease and psoriasis." (PMID 35322149, 2022). "Accordingly, EGF is induced by oxidative stress and is also increased in lung adenocarcinoma and head and neck carcinoma with mutationally activated NRF2." (PMID 33916908, 2021). "Lung adenocarcinoma harbours numerous molecular abnormalities, including mutation of the epidermal growth factor (EGF), rearrangement of the gene for anaplastic lymphoma kinase (ALK), and mutations for Kirsten rat sarcoma viral oncogene homologue (KRAS)." (PMID 33425389, 2020). "The findings supported that Twist expression was linked to EGFR mutations by collaborating with the EGF pathway in promoting EMT in EGFR mutated lung adenocarcinoma." (PMID 29581870, 2018). "Studies have shown that the prevalence of epidermal growth factor mutations (EGFR) mutation in PSC is similar to that of lung adenocarcinoma with a range of 0%–28%." (PMID 29423107, 2018). "Sixteen patients (15%) received molecular targeted therapy, and 12 patients with epidermal growth factor mutation positive lung adenocarcinoma were administered oral tyrosine kinase inhibitors." (PMID 27978813, 2016). "We also indicated that EGF stimulated a significant increase in the expression of CXCR4 in lung adenocarcinoma cells harboring the EGFR-L858R mutation." (PMID 26338423, 2015). "The present result strongly re-emphasizes that EGF signaling status in cancer cells underlies an aggressive phenotype of cancer cells, which is useful for the selection of early-stage lung adenocarcinoma patients with a poor prognosis." (PMID 23028479, 2012). "This study further demonstrates that genetic susceptibility to the EGF gene is associated with the occurrence of lung adenocarcinoma in younger patients, suggesting that the EGF gene may be a potential target for lung adenocarcinoma screening." (PMID 40696566, 2025). "This suggests that EGF polymorphisms may have potential value in the diagnosis, treatment, and even prognosis of young lung adenocarcinoma patients, but this conclusion urgently requires confirmation through larger sample sizes." (PMID 40696566, 2025). "The findings of this study regarding the EGF gene rs1897990 and rs1524106 also suggest that the T allele variants at these two loci represent high‐frequency adverse mutations, increasing the risk of lung adenocarcinoma in young patients." (PMID 40696566, 2025). "Additionally, smoking may enhance the risk of EGF rs1897990 and rs1524106 variants threatening the development of lung adenocarcinoma." (PMID 40696566, 2025).
lung adenocarcinoma (continued). "This study proposes developing and validating a novel impedimetric electrochemical biosensor for the sensitive and accurate detection of EGF in serum samples from patients with lung adenocarcinoma." (PMID 42030491, 2026). "The downregulation of angulin-1/LSR induces the malignancy of lung adenocarcinoma via EGF-dependent CLDN-2 and TGF-β-dependent cell metabolism." (PMID 38338691, 2024). "In this process, CLDN3 overexpression is modulated by the EGF pathway and has been observed to promote the malignant potential of lung adenocarcinoma." (PMID 39720074, 2024). "The loss of angulin-1/LSR promotes the malignancy via EGF-dependent CLDN-2 and TGF-β-dependent cell metabolism in human lung adenocarcinoma." (PMID 38338691, 2024). "CRISPR knockout screening in human A549 lung adenocarcinoma cells identified 5 EGF-resistance genes, and further RNAi validation showed DUSP1 increased survival of EGF treated cells, providing a novel target for EGFR-overexpressing cancers." (PMID 38816739, 2024). "When different concentrations of EGF were added to lung adenocarcinoma A549 cells, the protein expression level of EGFR increased to different degrees." (PMID 36674593, 2023). "Overexpression of CLDN-3 also promotes the malignancy of lung adenocarcinoma via EGF-activated MEK/ERK and PI3K/Akt pathways." (PMID 36961882, 2023). "In the present study, the EGFR tyrosine kinase inhibitor AG1478 prevented the upregulation of CLDN-2 at the protein and mRNA levels induced by EGF in lung adenocarcinoma cell line A549." (PMID 36961882, 2023). "This is the first study to highlight the formation of this complex under EGF in head and neck cancer, following the article on lung adenocarcinoma where this interaction was confirmed by FRET (fluorescence resonance energy transfer) and immunoprecipitation." (PMID 37576898, 2023). "A complementary study demonstrated that MAPK signalling regulated epidermal growth factor- and interferon-gamma-induced PD-L1 expression in lung adenocarcinoma cells and that inhibition of MEK1/2 attenuated PD-L1 upregulation." (PMID 35228614, 2022). "SP-D has also been shown to interrupt epidermal growth factor (EGF) signaling by blocking the EGF–EGFR interaction in human lung adenocarcinoma A549 cell line." (PMID 35874783, 2022). "For example, in a previous study, we reported that the pulmonary surfactant protein D (SP-D) downregulates EGF signaling in lung adenocarcinoma." (PMID 35089466, 2022). "Here we compared the impact of treating A549 lung adenocarcinoma cells with TGFβ, EGF, and both in combination by applying videomicroscopy, functional assays, immunoblotting, real-time PCR, and proteomics." (PMID 33777943, 2021). "We previously reported that IFNγ enhanced PD‐L1 expression in the A549 lung adenocarcinoma cell line, while EGF enhanced PD‐L1 in the PC‐9 lung adenocarcinoma cell line, but the opposite is not true." (PMID 33491334, 2021). "Herein, we report the impact of EGF+61 A>G genotype over ORR and DCR to first‐generation TKIs (erlotinib and gefitinib) on 111 EGFR‐mutated Brazilian lung adenocarcinoma patients." (PMID 32881389, 2020). "Thereafter, we investigated the association between EGF+61 A>G genotype and TKI response in a Brazilian series comprised of 111 TKI‐treated lung adenocarcinoma patients harboring EGFR‐sensitizing mutations." (PMID 32881389, 2020). "Our experiments demonstrated that both EGFR and MEK1/2 inhibitors decrease EGF‐ and IFNγ‐induced PD‐L1 expression, potentially increasing immunogenicity of lung adenocarcinoma cells." (PMID 30972766, 2019). "Treatment of human lung adenocarcinoma A549 cell line with SP-D has been shown to suppress the epidermal growth factor (EGF) signaling by interrupting the EGF–EGFR interaction, thus reducing cell proliferation, invasion, and migration." (PMID 30158928, 2018).
lung adenocarcinoma (continued). "Results of those studies revealed that epithelial-mesenchymal transition, EGF pathway activation, and MET amplification are all significantly associated with increased invasion and migration in lung adenocarcinoma cells resistant to EGFR-TKI." (PMID 29463039, 2018). "Recently, an interaction between the CRD region of human SP-D and N-glycans of EGFR has been reported which led to downregulated EGF signaling in human lung adenocarcinoma, A549 cell line cells." (PMID 29915574, 2018). "We further investigated this phenomenon by studying the expression of EINCR1 and other EGF-inducible lncRNAs in an independent dataset from lung adenocarcinomas." (PMID 28732076, 2017). "EGF treatment caused the expected transient induction of FOS in these cells and also a more sustained activation of EINCR1 in these lung adenocarcinoma cells." (PMID 28732076, 2017). "It has also been shown that EGF can upregulate the surface expression of TRPM7 proteins and the amplitude of TRPM7 currents, which are important for the basal and the EGF-enhanced cell migration of human lung adenocarcinoma A549 cells." (PMID 23594099, 2013). "A 58-year old man required thoracotomy (major surgery) without surgical resection of the lung nine months after starting CIMAvax® EGF for adenocarcinoma of the lung." (PMID 24127898, 2013). "For example, one of the standard second line therapies of lung adenocarcinoma in the U.S. is the use of epidermal growth factor (EGFR) antagonist, erlotinib, which inhibits tyrosine kinase activity of EGFR." (PMID 18478076, 2008). "Polymorphic analysis of EGF rs1897990 and rs1524106 in lung adenocarcinoma." (PMID 40696566, 2025). "In lung adenocarcinoma, the rs1897990 C allele may enhance the activity of the EGFR signalling pathway and promote tumor cell survival and metastasis by upregulating EGF." (PMID 40696566, 2025). "We hypothesized that LAD1 overexpression-mediated K-Ras addiction in lung adenocarcinoma may integrate with EGF signaling and influence its common downstream effector." (PMID 36770773, 2023). "Endocytosis of NE by the lung adenocarcinoma cells caused upregulation of PI3K-AKT survival signalling, whereas in PCa, extracellular NE triggered ERK signaling via the combined activation of receptor tyrosine kinases AXL and EGF." (PMID 35874783, 2022). "For example, hesperidin (approximately 10 μM) found in C. tangerine peel suppressed lipopolysaccharide-induced ERK1/2 phosphorylation in HaCaT cells, and naringin (100 μM) isolated from C. grandis attenuated EGF-induced ERK1/2 phosphorylation in human lung adenocarcinoma cells." (PMID 33096942, 2020). "Moreover, proliferation of lung adenocarcinoma cells induced by EGF has been shown to rely on CerK, responsible for C1P generation, which subsequently leads to ERK1/2 and Akt activation." (PMID 29300303, 2018). "We treated A549 lung adenocarcinoma cells containing mutations in KRAS (homozygous G12S mutation) with either ERK1/2 or MEK inhibitors (SCH772984 and PD0325901, respectively) prior to stimulation with EGF, similar to the protocols that we used for HeLa cells." (PMID 28982763, 2017). "In lung adenocarcinoma studies in the Chinese population, carriers of the rs1897990‐T allele had a significantly increased risk (OR = 1.32, 95% CI: 1.08–1.60), possibly related to aberrant activation of EGFR signalling driven by EGF overexpression in the tumor microenvironment." (PMID 40696566, 2025). "Furthermore, MEK signalling has also been shown to regulate PD-L1 expression in tumour cells specifically via epidermal growth factor- and interferon-gamma-induced PD-L1 expression in lung adenocarcinoma cells and blockade of MEK1/2 attenuated PD-L1 upregulation." (PMID 35228614, 2022). "The only cell line in this work in which PI3Kα appeared dispensable for EGF-induced PI3K signaling was A549, a lung adenocarcinoma cell line with amplified EGFR." (PMID 39706867, 2025).